MYC (MYC proto-oncogene, bHLH transcription factor)
Diseases named in the same sentence as MYC in open-access papers (continued):
Sharing a sentence is not in itself a finding about the gene and the disease.
lung adenocarcinoma (continued). "NCL overexpression suppresses CD8+ T cell glucose metabolism and anti-tumor immune function, promoting lung adenocarcinoma progression via the MYC/TXNIP axis." (PMID 40346484, 2025). "The loss of MGA in lung adenocarcinoma cells, which occurs in ~8% of lung adenocarcinoma patients, was shown to lead to an upregulation of MYC- and E2F6-target genes, resulting in an increase in cancer cell proliferation and invasiveness." (PMID 38454121, 2024). "For instance, hepatocarcinoma (HCC) with MYC amplification diminishes glutamine anabolism, while MYC-induced lung adenocarcinoma engages glucose catabolism and increases glutamine levels." (PMID 38216787, 2024). "Combination treatment greatly affects cancer hallmarks such as MYC targets and MTORC1 signaling, and also profoundly inhibits the activation of AKT, which has been implicated in squamous transition of lung adenocarcinoma." (PMID 39687207, 2024). "In conclusion, the present study provided evidence that UBQLN family members, especially UBQLN1 and UBQLN2, regulate MYC in lung adenocarcinoma cells." (PMID 37444499, 2023). "We performed a cell migration assay following a combined siRNA-mediated knockdown of either UBQLN1 or UBQLN2 with MYC in lung adenocarcinoma cell lines A549 and HOP62." (PMID 37444499, 2023). "Immunofluorescence staining of MYC revealed a drastic increase in nuclear expression following the loss of UBQLN1 or UBQLN2, or a combined loss of both UBQLN1 and UBQLN2 in lung adenocarcinoma cells." (PMID 37444499, 2023). "We demonstrate that there is a critical balance between UBQLN1 and MYC, driving cellular processes including cell viability, cell proliferation, cell migration, and clonogenic potential in lung adenocarcinoma cells." (PMID 37444499, 2023). "In vitro, primary lung adenocarcinoma cells were inhibited by miR-1827 when MYC or FAM83F overexpression was present." (PMID 37986065, 2023). "Taken together, our results suggest for the first time a novel role of UBQLN1 and UBQLN2 in regulating MYC in lung adenocarcinoma cells." (PMID 37444499, 2023). "In the present study, we provided evidence that UBQLN1 and UBQLN2 regulate MYC stability in lung adenocarcinoma cells." (PMID 37444499, 2023). "Omomyc was previously shown to exert a strong dominant negative effect on MYC promoting Ras-induced lung adenocarcinoma development." (PMID 37400551, 2023). "This can increase the modification of m6A in c-MYC mRNA and recruit YTHDF1 to promote the translation of c-MYC mRNA, ultimately accelerating the glycolysis and proliferation of lung adenocarcinoma cells." (PMID 37582735, 2023). "Immunofluorescence staining of MYC revealed a drastic increase in nuclear expression of MYC following the loss of UBQLN1 and/or UBQLN2 in lung adenocarcinoma cells." (PMID 37444499, 2023). "Neidler and coworkers in their study showed MYC accelerates KRasG12D-driven lung adenocarcinoma development." (PMID 37444499, 2023). "The effects of miR-1827 on primary lung adenocarcinoma cells in vitro were reduced by overexpressing MYC or FAM83F." (PMID 37986065, 2023). "Downregulated FTO in lung adenocarcinoma increases YTHDF1 binding to MYC mRNA, promotes MYC mRNA translation, and subsequently promotes tumour cell glycolysis, proliferation, and tumorigenesis." (PMID 36358640, 2022). "Focal amplifications of lineage-specific SEs have been mechanistically dissected and addressed the assembly and function of SEs, crucial for MYC overexpression in two types of epithelial cancer, lung adenocarcinoma (LUAD) and endometrial carcinoma (UCEC)." (PMID 36139535, 2022). "In particular, a ~23 kb internal segment of the focal amplicons in LUAD corresponds to a sub-domain of a SE, termed MYC-LASE (lung adenocarcinoma SE), mapped by H3K27ac-ChIP-seq profiling in A549 cells." (PMID 36139535, 2022). "For example, MYC activation induces CCL9-mediated attraction of macrophages in both lung adenocarcinoma (LUAD) and pancreatic ductal adenocarcinoma (PDAC)." (PMID 36323660, 2022).
lung adenocarcinoma (continued). "Variations in ATAD2 in smokers were found in non-small cell lung cancer (NSCLC) patients, and ATAD2 amplification not only regulates MYC-dependent transcription but is also a major driver of MYC-promoting lung adenocarcinoma cell proliferation." (PMID 36008934, 2022). "Computational analysis of copy number variations and genome rearrangement as well as H3K27ac- and p300-ChIP-seq profiling validated the lung adenocarcinoma-specific in vivo assembly of MYC-LASE." (PMID 36139535, 2022). "On the contrary, in lung adenocarcinoma, the PVT1b isoform is expressed downstream of MYC and is induced by DNA damage and oncogenic signals, thus acting as a tumour suppressor." (PMID 34445233, 2021). "Contrary to liver tumors, MYC-driven lung adenocarcinomas exhibited elevated levels of glutamine as well as GS protein expression, proposing that both the tissue of origin and the genetic makeup determine the metabolic profile of tumors." (PMID 34503295, 2021). "A recent study revealed ITGB1-DT as an oncogenic lncRNA in lung adenocarcinoma (LUAD) that activates the ITGB1-DT/ITGB1/Wnt/β-catenin/MYC positive feedback loop." (PMID 34490250, 2021). "(A) Expression of MYC in human lung adenocarcinoma (LADC, n = 483), lung squamous cell carcinoma (LSCC, n = 486), and normal non‐transformed tissue (normal LSCC = 338, normal LADC = 347)." (PMID 34636321, 2021). "In the analyses of oncogenic gene sets, we found six gene sets (SINGH KRAS Dependency Signature, CAMP UP.V1 UP, MYC UP.V1 UP, RB P107 DN.V1 UP, E2F1 UP.V1 UP and CSR LATE UP.V1 UP) associated with lung adenocarcinoma." (PMID 33446784, 2021). "Further, the in 1995 established lung adenocarcinoma-derived cell line LXF-289 showed atypical effects upon MYC inhibition, as mRNA levels of the transcript were increased by KJ-Pyr-9 treatment." (PMID 33925297, 2021). "Investigation of lung adenocarcinoma cell line LXF-289 revealed similar results concerning the influence of MYC inhibition on cell survival, suggesting a conserved working mechanism on lung adenocarcinoma cells with MYC expression." (PMID 33925297, 2021). "MZF1 facilitates the transcription of c-MYC, and is responsible for growth, migration, and invasion of lung adenocarcinoma cells." (PMID 32042322, 2020). "Here, to investigate which oncogenic drivers co-operate with Zmat3 loss to promote neoplastic transformation, we utilized Zmat3 knockout mice in models of c-MYC-driven lymphomagenesis and KrasG12D-driven lung adenocarcinoma development." (PMID 33082333, 2020). "The two different focal amplifications of SE 3′ to MYC in lung adenocarcinoma and endometrial carcinoma activate and boosts MYC promoter, which depends on lineage-specific chromatin loops and seRNA generation." (PMID 32278350, 2020). "Analysis of the TCGA (the cancer genome atlas) pan-cancer cohort of lung adenocarcinoma (LuAd) revealed amplification and/or overexpression of c-MYC in up to 20% of LuAd and a significant enrichment for MYC overexpression in KRAS mutant tumours (p = 0.025)." (PMID 31032816, 2019). "Increased expression of IL-23 and CCL9 by tumor cells additionally promotes recruitment and activation of macrophages in the KrasG12D-driven lung adenocarcinoma model upon MYC amplification, as mentioned in the previous paragraph." (PMID 31611871, 2019). "We developed an inducible mouse model of progressive lung adenocarcinoma (LuAd) that combines sporadic activation of oncogenic KRasG12D with modest overexpression of c-MYC (KM model)." (PMID 31032816, 2019). "In the second patient studied, suffering from lung adenocarcinoma, all the cells had a large amplification (100 Mbp) on chromosome 8 (up to over 10 copies) harboring, among others, the c-MYC gene." (PMID 29494651, 2018). "In a retrospective analysis in lung adenocarcinomas, c-MYC copy number gain was an independent poor-prognostic factor for disease-free and overall survival, with a possible association with EGFR mutation status." (PMID 29507657, 2018).
lung adenocarcinoma (continued). "Another molecular event cooperating with KRAS in driving lung adenocarcinoma development is represented by MYC activation." (PMID 30060526, 2018). "Reduction in tumor proliferation and increase in apoptosis was observed after inhibiting the COX and 5-LOX pathways in high MYC mice, highlighting these pathways as potential drug targets for lung adenocarcinoma." (PMID 27916803, 2016). "For instance, expression of a dominant-negative inhibitor of MYC heterodimerization in the mouse model for lung adenocarcinoma resulted in tumor regression." (PMID 27366943, 2016). "Outside these two malignancies, MYC appears strongly connected to STK11 in lung adenocarcinomas, a kinase related with global regulation of cell metabolism among other processes." (PMID 26792175, 2016). "For example, chr13, which contains the MYC gene that is commonly amplified in human lung adenocarcinoma, has 2-copy gains in both cell lines." (PMID 26560147, 2015). "In lung adenocarcinomas induced by MYC and/or K-rasG12D, tumors exhibited activation of the K-Ras/Stat3 signaling pathway." (PMID 18461184, 2008). "Using lung adenocarcinoma cell lines, we observed an increase in cell viability, clonogenic potential, and cell migration following the loss of either UBQLN1 or UBQLN2, which was associated with an increase in MYC expression." (PMID 37444499, 2023). "In addition, ADAM2-expressing human LUAD also exhibited increased expression of E2F, G2M and MYC, targets known to accelarate lung adenocarcinoma progression." (PMID 37258521, 2023). "The first example is MYC in KRAS-driven lung adenocarcinoma (LUAD)." (PMID 37142594, 2023). "Next, to determine whether protein synthesis is responsible for increased MYC levels following the loss of UBQLN1 or UBQLN2, we treated lung adenocarcinoma cell lines with protein synthesis inhibitor cycloheximide." (PMID 37444499, 2023). "In addition, the Zhang group deleted approximately 1.5 kb of the MYC enhancer located 450 kb downstream of the 3′ end in lung adenocarcinoma cells." (PMID 35039581, 2022). "For example, METTL3 increased m6A modification of PCAT6, resulting in PCAT6 upregulation in an IGF2BP2-dependent manner; LCAT3 stability was significantly increased in a METTL3-dependent manner in lung adenocarcinomas, thereby activating MYC transcription via FUBP1." (PMID 35037556, 2022). "ITGB1-DT could form a positive feedback loop with ITGB1/Wnt/β-Catenin/MYC to facilitate lung adenocarcinoma progression." (PMID 35047414, 2021). "In lung adenocarcinoma and endometrial carcinoma, MYC overexpression was driven by focally amplified SE, which could be a potential common mechanism for upregulating oncogene expression in epithelial cancers." (PMID 33854062, 2021). "To gain insight into how RET fusions may activate growth, we used transcriptomic profiling of RET-driven lung adenocarcinomas, which highlighted an enhanced MYC signature in these tumors." (PMID 33318047, 2020). "One reason for the failure to directly target MYC, at least in SCLCs, is that, unlike the epidermal growth factor receptor mutations or anaplastic lymphoma kinase rearrangement in lung adenocarcinomas, MYC de-regulation is not a sole driver aberration." (PMID 28192473, 2017). "MZF1 may be involved in an early stage of hematopoiesis and plays a role in terminal differentiation–especially of granulocyte lineage, it has also been shown to regulate c-MYC expression in lung adenocarcinoma." (PMID 27551915, 2016). "More recently, expressing a dominant-negative c-MYC allele in a KRAS- dependent murine model of lung adenocarcinoma further demonstrated the therapeutic benefit of c-MYC inhibition." (PMID 24796395, 2014). "In this study, we show that in the GSEA analysis of TCGA lung adenocarcinoma RNA-seq data, the KEAP1 mutations in R320 and R470 were associated with enhanced Tumor Necrosis Factor alpha (TNFα) – Nuclear Factor kappa subunit B (NFκB) signaling as well as MYC and MTORC1 pathways." (PMID 38184997, 2024).
lung adenocarcinoma (continued). "Thus, MYC induction by the CCSP promoter is sufficient to induce lung adenocarcinomas." (PMID 18461184, 2008). "These outcomes suggest that TXNIP overexpression can reverse the promoting effects of MYC on the infiltration ability of CD8+ T cells, thereby promoting the growth, invasion, and survival of lung adenocarcinoma cells." (PMID 40346484, 2025). "The amplifications of MYC, YAP1, and MMP13, as well as the deletion of CDKN2A/B, contributed to LC-BrMs originating from lung adenocarcinoma." (PMID 39593114, 2024). "A recent study demonstrated that the LPCAT gene was upregulated in a lung adenocarcinoma tissue and cell line, and LPCAT at least partially influenced lung adenocarcinoma metastasis through the PI3K/AKT signal pathway by targeting MYC transcription." (PMID 37309281, 2023). "CTCF, MLLT1, and TGIF2 are transcriptional regulators that play crucial roles in the transcription of important proto-oncogenes such as FOXM1, MYC, HoxA gene family, and OCT4 in multiple cancer types including HCC, esophageal cancer, and lung adenocarcinoma." (PMID 37335919, 2023). "In lung adenocarcinoma, LKB1-depleted cells promote cancer cell growth, spread, and invasion through the MZF1/MYC axis." (PMID 37654657, 2023). "For comparison, we included lung adenocarcinoma (LUAD)-R3 and LUAD-R4, two SE of MYC known to exhibit high and low activity, respectively, in lung adenocarcinoma cells." (PMID 35039581, 2022). "On the other hand, lung adenocarcinoma (LUAD, 115%) exhibited the greatest cumulative c-MYC pathway change frequency among all tumours." (PMID 35801728, 2022). "Blocking zDHHC20-mediated EGFR S-acylation has also been shown to reduce PI3K signaling and MYC levels and suppress cell growth in vitro and tumor growth in an in vivo model of KRAS-mutant lung adenocarcinoma." (PMID 36087837, 2022). "Overexpression of the MYC gene was also observed in lung SQCC tissue, compared to lung adenocarcinoma tissue." (PMID 34439333, 2021). "Immunocytochemical analysis of the MYC and NMYC expression of the well-established lung adenocarcinoma cell line LXF-289 revealed similar expressions for MYC and a slightly lower amount NMYC in comparison to BKZ populations." (PMID 33925297, 2021). "Immunohistochemical (IHC) staining performed on 12 lung adenocarcinoma (LA) tissue samples showed protein expression of OCT4, NANOG, SOX2, KLF4 and c-MYC, and the CSC marker CD44." (PMID 34685477, 2021). "Our finding that FTO downregulation induced by Wnt/β-catenin signaling enhanced c-Myc expression through upregulation of m6A of MYC mRNA and subsequent YTHDF1 binding revealed a novel mechanism by which lung adenocarcinoma promotes glycolysis and growth." (PMID 33966037, 2021). "The most significantly focally amplified genes in lung adenocarcinomas are NKX2-1, MYC, TERT, MCL1 and MDM2, while in LSQCC the most amplified were SOX2, CCND1, FGFR1, MYC, YES1, MIR205 and EGFR." (PMID 30060526, 2018). "CRISPR/Cas9‐mediated deletion (1,555–1,727 bp) of a part of the super‐enhancer region of MYC, which is bound by the transcriptional co‐activator EP300, reduced the expression of MYC by ~30% in human H2009 lung adenocarcinoma cells." (PMID 28255028, 2017). "In recent research on adenocarcinoma of the lung, patients with > 2 c-MYC copies/nucleus were classified as having an increased c-MYC GCN, which was found to be an independent poor prognostic factor." (PMID 26426996, 2015). "The expression levels of AREG, BIRC3, DKK1, EREG, FOSL1, MYC, and PLAU are negatively correlated with the survival ratio, and are significantly higher in the TSPX-low lung adenocarcinoma samples, compared to TSPX-high lung adenocarcinoma samples." (PMID 39858622, 2025).
lung adenocarcinoma (continued). "Collectively, our findings suggest that pathologic downregulation of TSPX in NSCLC, especially in lung adenocarcinoma, results in upregulation of AREG, EREG, FOSL1, MYC, and PLAU, thereby potentiating the EGFR signaling pathway and leading to the initiation and/or exacerbation of cancer development." (PMID 39858622, 2025). "Overall, these results indicate that NCL overexpression can relieve the transcriptional suppression of TXNIP by MYC, leading to decreased activity and cytotoxicity of CD8+ T cells, ultimately promoting the growth, invasion, and survival of lung adenocarcinoma cells." (PMID 40346484, 2025). "Moreover, the USP13-mediated deubiquitination process directly upregulated MYC protein levels with increased expression of SOX2 and squamous features in KP mouse and human lung adenocarcinoma cells." (PMID 38093367, 2023). "Here, we report a case of a patient with metastatic ALK-positive lung adenocarcinoma with an impressive resistance to sequential treatment with ALK TKIs mediated by YES1 and MYC amplification in a contest of epithelial-to-mesenchymal transition and high progressive chromosomal instability." (PMID 35199053, 2022). "MYC and KRAS act as downstream conduits for other oncogenic drivers, enhancing the process of tumourigenesis in lung adenomas and their transformation to invasive and proliferative adenocarcinoma of the lung." (PMID 34445233, 2021). "In lung adenocarcinoma, the molecular function of MGA appears to be antagonistic to that of MYC." (PMID 33920880, 2021). "The human cancer lines Hela (cervical), Calu-6 (lung adenocarcinoma), NCI-H841 (small cell lung cancer) and DU-145 (prostate) are all known to express MYC abundantly and treatment with diMF for four days killed 25–35% of cells with all four of these cell lines." (PMID 33760847, 2021). "Moreover, MYC amplification resulted in increased expression of IL-23 and CCL9 by tumor cells in lung adenocarcinoma murine models, which led to a rapid decrease of B, T, and NK cells, while macrophages were increasingly recruited and activated in the TIME." (PMID 31611871, 2019). "Notably, c-MYC gain is a poor-prognostic factor for disease-free survival (DFS) and overall survival (OS) in lung adenocarcinoma." (PMID 29494651, 2018). "Consistent with other reports for lung adenocarcinoma, JQ1 had little impact on MYC mRNA." (PMID 26485762, 2015). "We also showed heterogeneity in lung adenocarcinoma in never smokers with MYC as important in the classification." (PMID 21151896, 2010). "In contrast, MYC failed to cooperate with K-rasG12D to induce lung adenocarcinomas (compare CM, CR and CMR mice)." (PMID 18461184, 2008). "Taken together, our results suggest that TSPX may suppress the development and/or progression of lung adenocarcinoma by downregulating AREG, BIRC3, DKK1, EREG, FOSL1, MYC, and PLAU, which could exacerbate lung adenocarcinoma, and upregulating the tumor suppressor CACNA2D2." (PMID 39858622, 2025). "To further demonstrate the link between the three transcriptional regulators: MYC, EZH2 and YAP/TAZ and the tumor suppressor PTEN, we downloaded a list of transcripts and proteins positively or negatively correlated to PTEN in LUAD patients from the lung adenocarcinoma TCGA, Firehose Legacy study." (PMID 39455556, 2024). "Interestingly, we observed an increase in the expression of oncogene MYC following the loss of UBQLN1 or UBQLN2, but not with UBQLN3 or UBQLN4 in lung adenocarcinoma cells." (PMID 37444499, 2023). "Not regulated in LCSC-like cells but regulated in the lung adenocarcinoma cell line LXF-289 were lactate dehydrogenase A (LDHA) and MYC mRNA expressions, as LDHA was significantly reduced and MYC significantly increased after KJ-Pyr-9 application." (PMID 33925297, 2021). "Multiple genetic pathways defined by gains of MYC, deletions of RB1 and WRN or gains on 7p and 7q are involved in lung adenocarcinoma in never smokers." (PMID 21151896, 2010).